STAT3 (signal transducer and activator of transcription 3)
Diseases named in the same sentence as STAT3 in open-access papers (continued):
Sharing a sentence is not in itself a finding about the gene and the disease.
Obesity (continued). "Mice with neuronal-specific deletion of STAT3 also display severe obesity, decreased linear growth, and infertility, similarly to db/db mice." (PMID 32731387, 2020). "An important cancer survival pathway activated in obesity is signal transducer and activator of transcription 3 (STAT3)." (PMID 32722030, 2020). "In fact, up-regulation of SOCS3 in proopiomelanocortin (POMC) neurons leads to impairment of STAT3 signaling, with consequential leptin resistance and obesity, as well as glucose intolerance." (PMID 32630697, 2020). "One promising pathway explaining the relevance between obesity and cancer is the STAT3 signaling pathway." (PMID 32722030, 2020). "For example, chronic inflammation brought on by obesity results in increased expression of signal transducer and activator of transcription 3 (STAT3) and nuclear factor-κB (NF-κB), which increase cellular proliferation and pro-survival gene expression." (PMID 32050713, 2020). "For example, it has been demonstrated that the epigenetic silencing of miR-200c is capable of targeting STAT3-G9a signaling and limiting the malignancy of obesity-related breast cancer." (PMID 33121472, 2020). "On the other hand, conditional inactivation of IL-6 receptor or STAT3 has shown to prevent metabolic disturbance including obesity and insulin resistance." (PMID 32655424, 2020). "Overall, our results show VA induces STAT3-mediated autophagy to inhibit cancer growth and thermogenesis to ameliorate obesity in COC." (PMID 32722030, 2020). "Dimerized STAT3 acts as a transcription factor and upregulates SOCS3 expression, which can induce hypothalamic leptin resistance linked to obesity." (PMID 33379198, 2020). "A course of 8-week IL-4 supplementation improves common phenotypes of obesity and impaired signaling pathways of Akt, STAT3, and STAT6 in the hypothalamic, hepatic, and epididymal fat tissues." (PMID 32585823, 2020). "To further explore the effect of ISE on the decrease of pro-inflammatory mediators through JAK/STAT3 signaling pathway in the obesity-related environment, we measured the protein expression level of p-STAT3 and STAT3 in LPS and L1CM, respectively." (PMID 30863401, 2019). "Another study demonstrated increased STAT3 phosphorylation and expression in the hearts of Zucker rats, a genetic model of obesity." (PMID 30424579, 2018). "In line with this fact, inactivation of leptin receptor or dephosphorylation of STAT3 in POMC neurons reduces energy expenditure and increased food intake, thereby causing obesity in db/db mice." (PMID 29979770, 2018). "As a direct transcriptional product of STAT3, SOCS3 is commonly thought to play a pathophysiological role in obesity-associated leptin resistance." (PMID 29615796, 2018). "This is in line with our previous publication in which we postulated a STAT3-inducing factor in obesity to adopt IL-6 signaling in HCC development of IL-6Rα-deficient mice." (PMID 30224299, 2018). "Mechanistically, obesity-induced pro-inflammatory STAT3 and AR-induced signaling cooperatively up-regulated CCRK expression, which in turn activated the mTORC1 pathway crucial for lipid/glucose homeostasis, immunosuppression, and tumorigenesis." (PMID 30523261, 2018). "There is a shortage of studies investigating the effect of obesity on ischaemic or pharmacological conditioning-induced cardiac STAT3 activation after ischaemia/reperfusion." (PMID 30424579, 2018). "Mice with pancreatic beta-cell-specific disruption of the STAT3 gene exhibited increased appetites, obesity, partial leptin resistance, and glucose intolerance." (PMID 29596388, 2018). "Deletion of the LepR signaling molecule, signal transducer and activator of transcription-3 (Stat3), in POMC neurons causes mild obesity in female mice and reduces Pomc gene expression." (PMID 30304668, 2018).
Obesity (continued). "In this sense, our CAF-induced obesity rat model exhibited body weight/fat increase, hyperleptinemia and peripheral leptin resistance as indicated by the impairment of leptin-induced STAT3 phosphorylation in these tissues." (PMID 30441779, 2018). "In vitro studies reported that STAT3 deletion interferes with normal body weight homeostasis and glucose metabolism, leading to obesity, diabetes, and thermal dysregulation." (PMID 29596388, 2018). "When fed HF/HSD, Ptprj-KO mice also gradually got obese due to a decrease in leptin sensitivity as judged by the activation of STAT3, but they exhibited attenuated development of leptin resistance with obesity." (PMID 28912580, 2017). "Consistently, increased SOCS3 expression in POMC neurons results in impaired STAT3 signaling with subsequent leptin resistance and obesity." (PMID 28270795, 2017). "In fact, fatty acid binding protein 4 (FABP4)/IL-6/STAT3/DNA methyltransferase 1 (DNMT1) have been shown to link obesity to the growth of AML cells." (PMID 29269861, 2017). "We find that obesity due to chronic exposure to a high fat diet impairs sensing of leptin (as measured by STAT3 phosphorylation in response to exogenous leptin) throughout the brain, which is congruent with similar studies in rodents and humans." (PMID 28107353, 2017). "Mice in which STAT3 is specifically deleted in ObRb neurons similary develop hyperphagic obesity with some preservation of glucose homeostasis." (PMID 28270795, 2017). "Overall this study demonstrates that early-onset obesity as a result of maternal HFD during lactation does not only dysregulate intrinsic-pulmonary STAT3-AMPKα-SOCS3, but also activate AKT/GSK3β pathway, indicative for insulin signaling." (PMID 27087690, 2016). "More recently, we treated ThrbPV/PVPten+/−mice with a STAT3-specific inhibitor, S3I-201, aiming to block the STAT3-downstream signaling to delay obesity-exacerbated thyroid cancer progression." (PMID 27145454, 2016). "Curcumin as a treatment for obesity and obesity-related metabolic diseases has been shown extensively through suppressing the proinflammatory NF-κB, signal transducer and activators of STAT3, and Wnt/β-catenin." (PMID 26007179, 2015). "Previous research has established that changes in the expression of SOCS3, leptin, and the activation of STAT3, and AMPK are linked to the regulation of insulin signaling in obesity and diabetes." (PMID 24997069, 2014). "Animal researches reveal that STAT3 acts to fight against obesity through various distinctive pathways." (PMID 25014397, 2014). "Increased SOCS-3 expression in POMC neurons inhibits activation of signal transducer and activator of transcription (STAT)-3 and results in hyperphasia and obesity." (PMID 23696840, 2013). "A similar degree of obesity and adiposity is seen in mice with inactivation of STAT3 in POMC neurons." (PMID 23341784, 2013). "Other kinases such as extracellular signal- regulated kinase (ERK) 1/2 and STAT3 have been also demonstrated to be involved in obesity." (PMID 23110196, 2012). "Taken together, regulation of the IL-6/STAT3/SOCS3 pathway in muscle cells seems to change with obesity, possibly due to alterations in circulating cytokine levels and composition." (PMID 22761857, 2012). "We here demonstrate that specifically arcuate POMC neurons of DIO mice are resistant to LepRb-STAT3 signaling, suggesting an important role of those particular neurons in the development and/or maintenance of diet-induced-obesity." (PMID 22276206, 2012). "Adipose STAT3/STAT5 ablation promoted obesity and suppresses lipolytic capacity." (PMID 41491570, 2026). "This circuit acts as a potent upstream activator of mTORC1 signaling in obesity-associated HCC, and is cooperatively induced by obesity-driven pro-inflammatory signals (the IL-6/STAT3 axis) and androgen receptor (AR) signaling—providing a molecular explanation for the male predominance in MASH-HCC." (PMID 41208895, 2025).
Obesity (continued). "Moreover, obesity-induced expression of lipocalin 2 also contributes to the activation of NF-κB and STAT3 to facilitate M1 macrophage polarization, exacerbating the insulin resistance and inflammation." (PMID 40863244, 2025). "Similarly, signal transducer and activator of transcription 3 (STAT3) signaling is sustained in obesity-related MASLD and HCC, driven by increased IL-6 and leptin." (PMID 40427086, 2025). "The inhibition of the STAT3 signaling pathway has shown promise in reducing visceral obesity, countering metabolic syndrome development, and preventing obesity-induced neuroinflammation." (PMID 40376303, 2025). "Nevertheless, the role of Stat3 in regulating macrophages/myeloid cells pertaining to obesity-induced insulin resistance remains unknown." (PMID 40801626, 2025). "Our demonstration that Jak2/Stat3 is persistently activated in the fat-laden adipose tissue microenvironment has important implications for understanding how pro-inflammatory ATM phenotypes are amplified during obesity." (PMID 40801626, 2025). "Specific deletion of STAT3 in neurons leads to profound obesity in mice." (PMID 41516046, 2025). "Combination therapies that simultaneously modulate AMPK, ERK, PKC, and STAT3 pathways could synergistically inhibit ET-1-mediated fat cell activity, obesity, and obesity-related complications while improving metabolic health." (PMID 41209557, 2025). "Furthermore, a body of evidence suggests that leptin-STAT3 signaling in the central nervous system is involved in the development of obesity and diabetes." (PMID 41170186, 2025). "Moreover, GC-induced macrophage deactivation disturbs the STAT3 signaling pathway in adipocytes, subsequently leading to obesity." (PMID 38331933, 2024). "Hyperleptinemia, which occurs in obesity-related metabolic disturbances, favors the synthesis of the thyrotropin-releasing hormone via the promotion of the synthesis of the α-melanocyte-stimulating hormone and the activation of the STAT3 transcription factor." (PMID 39202472, 2024). "Additionally, upregulation of FTO/CX3CL1 and suppressor of cytokine signaling 3 (SOCS3) in the hypothalamus impairs leptin- and signal transducer and activator of transcription 3 (STAT3) signaling, resulting in leptin resistance and obesity." (PMID 39125332, 2024). "POPs may also be linked to the development of obesity by increasing activation of the Notch pathway, by causing alteration of the TYK-2/STAT-3 pathway, and by increasing FABP expression and FAS upregulation, observed under in vitro conditions." (PMID 38255955, 2024). "It is known that the alteration of the TYK-2/STAT-3 pathway can increase obesity development." (PMID 38255955, 2024). "In mice, neural-specific STAT3 knockout and mutation of leptin receptors that do not bind STAT3 leads to hyperphagia, obesity, reduced energy consumption, and augmented mRNA level of AGRP." (PMID 37886966, 2023). "Grohmann and colleagues demonstrated that the oxidative hepatic environment in obesity restrained the STAT1 and STAT3 phosphatase TCPTP, which led to potentiate STAT1 and STAT3 signaling, and further increase the risk of developing NASH and HCC in the setting of nutritional excess." (PMID 37008925, 2023). "Put together, the gut modulatory effects of WG on STAT3 and AMPs may be vital to reduce the burden of obesity-induced adipose tissue inflammation and diet-induced insulin resistance." (PMID 37181127, 2023). "Moreover, increased serum leptin in obesity suppressed anti-Mullerian hormone gene expression through the JAK2/STAT3 pathway." (PMID 36726106, 2023). "Other downstream molecules or pathways that may play a role in lipedema include p-NF-κB and p-STAT3 as both have known correlations with obesity and adipose inflammation." (PMID 37887430, 2023).
Obesity (continued). "In this study, we constructed a co-expression network between obesity and PTC and identified four common hub genes (MNDA, TNC, CHIT1, MMP9) and two common TFs (ELF4, STAT3), which might provide new diagnostic and therapeutic strategies for obesity-related PTC." (PMID 37671970, 2023). "Taken together, these data suggest that HFD induces the IRF3, TGFβ1, and STAT3 signaling pathways in AT that in part might suppress the expression of PPAR-γ to maintain low-grade chronic inflammation in AT during HFD-induced obesity." (PMID 35456006, 2022). "Our previous study has proven that leptin/LepR signaling, an important adipocytokine signaling, could promote osteogenesis differentiation through STAT3 signaling pathway, which indicated the intrinsic interaction between obesity and OLF." (PMID 35712246, 2022). "Pharmacological blockade of mitoSTAT3 either by a mitochondria-targeted STAT3 inhibitor or ROS scavenging prevented obesity and fatty acid–induced production of proinflammatory cytokines IL-17A and IL-6, thus establishing a mechanistic link between mitoSTAT3 and inflammatory cytokine production." (PMID 35928250, 2022). "Therefore, the leptin-STAT3-FAO axis is the mediator between obesity and impaired anti-tumor immune response." (PMID 35062950, 2022). "During obesity, STAT3, a transcription factor for Th17 cytokines, is chronically activated." (PMID 35928250, 2022). "Similarly, we previously reported a link between early-onset overweight and obesity with activated IL-6/STAT3 signaling, increased airway resistance and lung remodeling." (PMID 35896539, 2022). "Moreover, the increased SOCS3 in the hypothalamus in turn suppresses JAK2/STAT3 signaling pathway, which forms leptin resistance, leading to hyperleptinemia and obesity." (PMID 36270984, 2022). "Notably, each advanced age and obesity resulted in enrichment of IL-6/JAK/STAT3 signaling, which cultivates an immunosuppressive environment by stimulating expansion of myeloid-derived suppressor cells and controlling antitumor T cell responses." (PMID 36686775, 2022). "Although there are many controversial studies on the effects of IL-6 on obesity, IL-6 must be the key in the process of energy metabolism and adipogenesis, which may involve pathways like IL-6/STAT3/AMPK and IL-6/STAT3/PPARγ." (PMID 36105933, 2022). "Oxidative hepatic environment in obesity models of NAFLD has been associated with increased STAT-1 and STAT-3 signaling and inactivated STAT-1 and STAT-3 phosphatase T cell protein tyrosine phosphate (TCPTP), promoting hepatic T cell recruitment, NASH, fibrosis and HCC." (PMID 36544761, 2022). "Finally, we examined the effects of GRIM19 on the Th17/Treg balance, which is modulated by the STAT3 pathway, in our mouse model of obesity." (PMID 33467683, 2021). "Interestingly, we and others have shown that deleting STAT3 from all LepRb-expressing cells results in obesity but uncompromised fertility, suggesting that STAT3 activation in non-LepRb cells is sufficient to protect reproductive function." (PMID 34502119, 2021). "In comparison, hAMSCs-CM effectively reversed HFD-induced decreases of ARG-1 and increase of the phosphorylated STAT3, suggesting that the anti-obesity of hAMSCs-CM might be involved in their anti-inflammation." (PMID 34174964, 2021). "Obesity-associated HCC development depended on the increased tumor-promoting cytokines IL-6 and TNF, inducing liver inflammation and activation of oncogenic signal transducer and activator of transcription 3 (STAT3) signaling in mice." (PMID 35002979, 2021). "In addition to PPARγ, the signal transducer and activator of transcription 3 (STAT3) is another important molecular player in obesity." (PMID 34602925, 2021). "We propose that some unknown factor(s), which are abundant in hypothalamus of normal mice but gradually missed along the development of diet-induced obesity, would be necessary for phosphor-STAT3 to act on its target genes." (PMID 33849593, 2021).
Obesity (continued). "The deletion of STAT3 in the CNS leads to severe obesity with accompanying decreased POMC expression, whereas STAT3 inactivation in POMC neurons causes slight obesity and diminished POMC expression, which suggest STAT3 as a transcriptional activator of POMC expression." (PMID 33849593, 2021). "In summary, obesity modulated both the STAT3/NFκB pathway and the WNK4 axis." (PMID 34489970, 2021). "This extract significantly down-regulates FTO via its highest binding affinity, but up-regulates the signal transducer and activator of transcription 3 (STAT-3) and reduces insulin resistance in high-fat diet-induced obesity in rats, possibly contributing to its use in the management of obesity." (PMID 34684698, 2021). "Furthermore, a specific deletion of Tyr1138 in LepRb or STAT3 in LepRb-expressing neurons leads to hyperphagia and obesity similar to the phenotype observed in db/db mice, suggesting that Tyr1138 in STAT3 is vital for leptin action." (PMID 33849593, 2021). "Moreover STAT3 acts as link between obesity and diabetes by mediating lipid-induced insulin resistance." (PMID 34416903, 2021). "These transcriptional regulators are also involved in glucose metabolism and interact with LPI and STAT3, factors that are also known to be a control point in obesity progression, which in turn has a strong relationship to the development and progression of EC." (PMID 34324032, 2021). "The ARH has not been primarily viewed as a dimorphic structure, but recent studies showed differences between males and females in the number of ARH POMC neurons, their firing rate, the development of diet-induced obesity, and the activation of STAT3 in POMC neurons." (PMID 33253166, 2020). "STAT3 is also a possible factor which links obesity and cancer." (PMID 32722030, 2020). "This supports the hypothesis that the activation of IL-6/STAT3 promotes the senescence of BMSCs in BM, suggesting a potential mechanism for trabecular bone loss in HFD-induced obesity." (PMID 33679606, 2020). "The Janus kinase (JAK)-signaling transducer and activator of transcription 3 (STAT3) pathway regulates key white adipocyte functions, and the severity of its deregulation in obesity correlates with important pathological outcomes, including leptin and insulin resistance." (PMID 31781039, 2019). "Importantly, PTP1B-deficient mice display the resistance to diet-induced obesity, augmented energy expenditure, hypersensitivity to leptin, and enhanced phosphorylation levels of JAK2 and STAT3 in the hypothalamus." (PMID 30383868, 2018). "Therefore, the activation of JAK2 or STAT3 in hepatocytes also ameliorates steatosis and improves lipid metabolism, which further contributes to anti-obesity action." (PMID 29874843, 2018). "Besides beneficial effects, chronic activation of STAT3 in obesity leads to constant expression of its own inhibitor, SOCS3, disrupting the homeostasis of the IL-6 signaling pathway." (PMID 30591653, 2018). "Moreover, T cell-mediated STAT3 promoted insulin resistance and obesity while leptin (satiety hormone) signaling relied on downstream STAT3 signaling." (PMID 30369883, 2018). "The mice lacking IL-21 or mice with specific deletion of STAT3 in T cells fed with HFD showed an increase of VAT Treg cells and an improvement of adipose inflammation and insulin sensitivity, suggesting an important role for IL-21 and STAT3 signaling in regulating VAT Treg cells in obesity." (PMID 30323806, 2018). "Based on the literature data, it seems that facilitated cardiac STAT3 signalling might contribute to activation of hypertrophic and surviving pathways in obesity." (PMID 30424579, 2018). "Thus, SR3306-mediated JNK inhibition enhances STAT3 as well as PI-3K signaling pathways, contributing to the amelioration of leptin resistance and obesity in the DIO mice." (PMID 28165482, 2017).